EGFR (epidermal growth factor receptor)
Diseases named in the same sentence as EGFR in open-access papers (continued):
Sharing a sentence is not in itself a finding about the gene and the disease.
tumor (continued). "Receptors such as epidermal growth factor receptor (EGFR) and receptor for a vascular endothelium growth factor (VEGF) have a role in tumor progression, and when mAbs are injected inhibit their effect." (PMID 38234663, 2024). "The efficiency of armored-T cells combined with different antibodies in lysing tumor cells was investigated in vitro using several targets, among which were CD20, HER-2 and EGFR." (PMID 38953027, 2024). "EGFR and VEGFR-2 appear closely related, having similar downstream signal transduction pathways and being crucial regulators in angiogenesis and tumor formation." (PMID 39443462, 2024). "Accordingly, the correlation of EGFR and GPER levels with clinical outcomes and aggressive features of BC, including the development of distant metastases and tumor size, has been assessed." (PMID 38886784, 2024). "IL11 functions as a ligand of EGFR, and this binding activates EGFR and downstream signaling to increase the expression of PDL1, culminating in the immune escape of tumor cells." (PMID 38696655, 2024). "Radiation therapy triggers PD-L1 expression in tumor cells through four primary mechanisms, DNA damage signaling, IFN-γ signaling, cGAS-STING, and EGFR." (PMID 38462628, 2024). "In a grade 3 TNBC patient-derived tumour xenograft (PDX) model in nude mice, mice engrafted with TNBC cells with high EGFR levels exhibited differential responses to EGFR-targeted drugs." (PMID 38604999, 2024). "EBV, and more precisely, its oncoproteins, initiate tumor formation by modulating many signaling pathways, such as NF-κB, JAK/STAT, Wnt/β-catenin, PI3k/Akt/mTOR and EGFR/MAPK." (PMID 39001390, 2024). "Preclinical studies have demonstrated the potent inhibitory effects of abivertinib on EGFR and HER2 activation, leading to significant suppression of tumor proliferation in animal models." (PMID 38611728, 2024). "For instance, polymeric NPs modified with EGF can target GBM cells overexpressing EGFR, while VEGF-modified polymeric NPs can enhance targeting of the TME, specifically within the tumor vasculature." (PMID 39834835, 2024). "These signaling cascades, including MAPK, JAK-STAT, and EGFR/PI3K/Akt/mTOR, orchestrate key oncogenic processes, while dysregulation in pathways like Wnt/β-catenin, VEGF/VEGFR, and NF-κB promotes tumor progression and angiogenesis." (PMID 39682234, 2024). "Hereby, RTKs and their downstream signaling, such as the EGFR/PI3K/AKT pathway are activated, which enable suppression of apoptosis and provide the tumor with resistance to therapeutic treatment." (PMID 39506058, 2024). "Results showed that the regulatory factors CRNDE, EDN1, JUNB, and MAP2K1/2, ZFP36 mainly regulate differentially expressed genes (VEGFA, EGFR, PLAUR) to regulate invasion of cells, invasion of tumor, and microtubule dynamics." (PMID 38711992, 2024). "In this study, we found that HPRT1 was overexpressed in EGFR-mutant LUAD cells and tissues, and HPRT1 promoted cell proliferation in vitro and tumor growth in vivo." (PMID 39343971, 2024). "Meanwhile, triple inhibition of EGFR, MET, and VEGF effectively inhibited tumor growth and angiogenesis of MET-driven EGFR-TKI resistant tumors." (PMID 39354638, 2024). "For instance, EGFR-TKI drugs, well-studied in tumor-targeted therapy, can induce autophagy in tumor cells." (PMID 38942606, 2024). "As such, EGFR signaling is frequently dysregulated in CRC to promote cell proliferation and tumor growth via receptor and/or ligand overexpression as well as downstream oncogenic mutations." (PMID 40727266, 2024). "However, EGFR mutations could not be detected in the DNA of tumor-educated platelets isolated from patients with NSCLC." (PMID 39727929, 2024).
tumor (continued). "MLN4924 showed several side effects including tumor sphere formation and ciliogenesis inhibition through the c-MYC accumulation and dimerization of EGFR, activating the EGFR signaling pathway." (PMID 38398217, 2024). "They reported that macrophages in the tumor microenvironment secrete EREG, which in turn leads to the formation of the EGFR/ErbB2 heterodimer and induces resistance to EGFR-TKIs through the activation of the PI3K/AKT pathway." (PMID 38398101, 2024). "AGRN was correlated with epidermal growth factor receptor (EGFR) protein and tumor necrosis status in immunohistochemical results." (PMID 39691475, 2024). "By inhibiting the TNIK/EGFR axis, NCB-0846 showed inhibitory effects on CRPC tumor cells both in vivo and in vitro and blocked EMT of tumor cells as well as bone metastasis." (PMID 38226156, 2024). "Our study found that the expression/infiltration of PD-L1, EGFR, and CD8+ T cells was increased in BMC tumour tissues vs. normal tissues." (PMID 39073672, 2024). "Numerous tumour pathways, including PI2K, EGFR and TGFb, demonstrated a close correlation with the involvement of ECM in LIHC." (PMID 38568083, 2024). "In vitro studies demonstrated the efficacy of poziotinib in EGFR- and human epidermal growth factor receptor-2 (HER2)-dependent tumor xenograft models." (PMID 38774882, 2024). "Mutant EGFR is overexpressed in 10% of white and 40% of East Asian NSCLC patients, leading to uncontrolled tumor growth." (PMID 39429333, 2024). "We report that the level of intratumoral DAG determines the response of anti-BRAF/EGFR therapy in BRAFV600E-mutant mCRC, enriching our understanding of DAG’s regulation of tumor-targeted therapy." (PMID 39436710, 2024). "More significantly, WntSI effectively overcame acquired resistance to EGFR‐TKIs resulting from MET amplification in both cell line‐derived and patient‐derived tumor xenograft mouse models, while demonstrating exceptional biosecurity." (PMID 38867713, 2024). "A detailed histopathological review and immunohistopathological staining for ER, PR, HER2/neu, AR, EGFR, and Ki-67 were performed on formalin-fixed paraffin-embedded (FFPE) tumor tissue blocks." (PMID 39439618, 2024). "We investigated the expression patterns of EGFR and MUC1 in patients with LUAD and CRC by IHC, and observed high expression of EGFR and MUC1 in tumor tissues." (PMID 39664199, 2024). "On the other hand, EGFR classifiers trained on CCLE and evaluated on TCGA performed considerably worse on human tumor samples as compared to held-out cell lines." (PMID 39776849, 2024). "Pathological classification of TNBC using EGFR, CK5/6, AR, cell-adhesion molecules, and tumor infiltrating lymphocytes (TIL) has been suggested to optimize treatment of TNBC." (PMID 37934318, 2024). "VHHs have been designed to bind tumor-specific targets TSAs such as HER2, EGFR, and VEGFR, over the past years and they are reported to have anti-tumor efficacy." (PMID 38254860, 2024). "Analysis of ligand-receptor pairs revealed interactions between CXCR1+ neutrophils and tumor cells involving TGFA-EGFR and EGF-EGFR, potentially explaining aspects of resistance to third-generation EGFR-TKIs due to sustained EGFR activation." (PMID 39638994, 2024). "Recent studies have shown that targeted oncogene therapy, which includes inhibitors of EGFR, ALK, KRAS, and BRAF, induces DNA double-strand breaks and activates the DDR pathway in residual tumor cells." (PMID 38776912, 2024).
tumor (continued). "Most studies suggested that elevated IRTKS expression or the activated fusion gene FGFR3-BAIAP2L1 promoted tumor growth and progression by activating FGFR3, epidermal growth factor receptor (EGFR) signaling, and known membrane protrusions." (PMID 39192031, 2024). "Taken together, these findings illustrated that KIF3C knockdown blocked the VASH2-induced enhancement of EGFR endosomal recycling and rescued LUSC tumor progression and chemoresistance." (PMID 39443476, 2024). "A recent work described tumor regression in two patients with GBM treated with a CAR-T strategy engineered to target EGFRvIII, as well as wild-type EGFR." (PMID 38727302, 2024). "Inhibit tumor growth; promote tumor apoptosis; the levels of p-SRC, p-EGFR, p-STAT3 and p-AKT are down-regulated." (PMID 39045282, 2024). "Osimertinib, an irreversible, orally administered EGFR-TKI, was initially approved by the FDA in 2015 and was intended for use only as an adjuvant therapy after tumor resection in adult NSCLC patients with EGFR exon 19 deletions or exon 21 L858 mutations." (PMID 39202551, 2024). "EGFR, the most prevalent molecule in the study, exhibited differential expression in CRG subgroups, contributing to tumor cell differentiation, proliferation, and migration by regulating several signaling pathways, including PI3K/AKT, RAS/MAPK, and JAK2/STAT." (PMID 38956740, 2024). "Firstly, as we showed the expression patterns of EGFR and MUC1 in a panel of normal tissues and various tumor tissues, the sample size was still limited to achieve a thorough comparison between tumor and normal tissues." (PMID 39664199, 2024). "Enhanced EGFR activity has been shown to modulate the activity of BMP downstream signaling molecules such as MAPK and PI3K/Akt to facilitate tumor invasion and motility." (PMID 39100096, 2024). "Another example is the co-administration of the EGFR-TKI osimertinib and T-DM1, which contributed to an synergistic anti-tumor effect, where T-DM1 was able to delay or overcome osimertinib resistance in EGFR-mutant NSCLC models." (PMID 38178200, 2024). "Therefore, in some cases, EGFR mutations found in ctDNA may not be completely consistent with those in tumor tissues." (PMID 39634906, 2024). "MET is present in the bypass pathway of the ERBB signaling pathway and is a proto-oncogene that interacts with EGFR, thereby promoting drug resistance of the tumor." (PMID 39628999, 2024). "In conclusion, the high-dose administration of CUR demonstrated its potential to suppress tumor growth and angiogenesis in caski-transplanted mice through the downregulation of VEGF, COX-2, and EGFR signaling pathways." (PMID 38751791, 2024). "EGF is released by tumor cells and binds to the EGF receptor (EGFR) on tumor ECs to promote EC migration and capillary tube formation." (PMID 38892305, 2024). "We further investigated the expression of 10 key genes in NSCLC cell subtypes, among which EGFR and VEGFA are significantly enriched in tumour cells." (PMID 38801409, 2024). "TGF-β also acts as EGFR agonist together with EGF, which triggers the activation of EGFR pathway inducing multiple pro-tumour effects in HNSCC." (PMID 38926351, 2024). "Thus, while our data suggest that negative hyperselection status may be more informative for treatment selection than tumor sidedness, further investigations are necessary to confirm whether anti-EGFR antibody therapy is truly beneficial for negatively hyperselected patients with right-sided mCRC." (PMID 38347302, 2024). "Together, our results illustrated the expression patterns of EGFR and MUC1 in tumor and normal tissues, and suggested that they were promising drug targets for developing cancer therapies targeting dual TAAs." (PMID 39664199, 2024). "Beyond EGFR, recent findings highlight the overexpressions of ERBB2 and ERBB3 in different tumor cohorts." (PMID 38473265, 2024).
tumor (continued). "Preclinical research in GBM has revealed that combining an EGFR inhibitor with a mTOR inhibitor can modulate the TME by downregulating immunosuppressive chemokines and inhibiting tumour-promoting macrophage infiltration." (PMID 39272879, 2024). "By inhibiting the generalization and degradation of EGFR signals, linc-ROR acts as a tumor promoter." (PMID 39130630, 2024). "This study demonstrated the efficient killing of EGFR+ CRC cells in vitro by EGFR-targeting CAR-T cells, which also suppressed tumor growth and prolonged survival in vivo." (PMID 39417449, 2024). "In the tumor microenvironment, GP73 recycles epidermal growth factor receptor (EGFR) back to the cell-surface under high EGF conditions, or directs it to lysosomes for degradation under low EGF conditions, conserving cellular energy." (PMID 39845976, 2024). "In summary, MET amplification in NSCLC cells and CD73 expression in MET-amplified EGFR-TKI-resistant cells can significantly reduce STING levels and anti-tumor T cell infiltration, thereby compromising the efficacy of ICB therapy for NSCLC." (PMID 38566036, 2024). "The irreversible pan-HER (HER1, 2 and 4) inhibitor afatinib induced a sustained inhibition of EGFR and HER3 as sufficiently as the dual blockade of lapatinib and trastuzumab and provided a durable tumor regression in vitro." (PMID 38611014, 2024). "Gefitinib, an EGFR inhibitor, can block AREG-EGFR signaling to relieve bone destruction in MM, while JQ1 acts on BMSCs to disturb CXCL8 synthesis and reveal anti-tumor efficacy." (PMID 38475811, 2024). "IgA mAbs anti‐tumor antigens (i.e., CD20, HER2, or EGFR) are able to engage FcαRI‐expressing cells promoting cell migration to tumor area and cell cytotoxicity." (PMID 39578936, 2024). "In vivo, FADU tumors were imaged with [89Zr]-pertuzumab (HER2) and [89Zr]-panitumumab (EGFR) and heterogeneity (as shown with histogram of the SUV of all tumor voxels) of uptake was quantified." (PMID 38355949, 2024). "There are cases of relapse in advanced CRC patients treated with EGFR-targeted monoclonal antibody therapy and this involves the outgrowth of previously undetected KRAS-mutant tumor cell populations." (PMID 39125664, 2024). "The Xmrk protein, similar to EGFR, activates the PI3K-AKT and RAS-RAF-MEK-MAPK signaling pathways, contributing to tumor progression." (PMID 38534309, 2024). "Fixed tissue sections from the tumor mice model treated with PBS, HUVEC-EVs, GE11-HUVEC-EVs, vinorelbine (Vin), and GE11-HUVEC-EVs-Vin were stained with DAPI, EGFR, and Ki67 (a marker for proliferating cells)." (PMID 39453005, 2024). "They found that miR-615 plays a tumor suppressor role in GBM cell proliferation, migration, and invasion by targeting EGFR expression." (PMID 39766391, 2024). "VEGF/PD-1 bsAb in combination with chemotherapy has shown anti-tumor response in advanced NSCLC and EGFR-TKI-failed NSCLC, with ongoing Phase III trials (NCT05184712)." (PMID 38785789, 2024). "Next, we examined HPAF-II tumor lysates from mice treated with ETC-159 and observed an increase in the phosphorylation of EGFR at Y1068 and EPHA2 at Y588." (PMID 38488003, 2024).
tumor (continued). "Particularly in CC, alterations in the ERK pathway have been detected, leading to clinical studies evaluating inhibitors of MAPK pathway such as EGFR inhibitors, Raf modulators, and MEK inhibitors to reduce tumor progression." (PMID 39629272, 2024). "EGFR is one of the most essential receptors in the progress of NSCLC tumorigenesis and tumor development." (PMID 38341588, 2024). "The detection of EGFR and PIK3CA amplifications in patients HN03 and HN06 illustrates the dynamic nature of tumor evolution and the development of resistance under ICI therapy." (PMID 39796090, 2024). "In general, our experiments confirmed that EGFR and PD-L1 were expressed at relatively higher levels in OSCC tumor tissues than in normal tissues." (PMID 39183296, 2024). "We then confirmed that the expression patterns of EGFR and MUC1 in tumor tissues by immunohistochemistry (IHC)." (PMID 39664199, 2024). "Patients with tumors showing EGFR, ALK or ROS1 gene alterations were excluded, and the PD-L1 tumor proportion score was determined." (PMID 38539510, 2024). "In terms of the tumor volume and weight, gefitinib treatment along with FZYA reduced the acquired resistance of EGFR-TKIs in lung ASC, and its inhibitory effect was superior to EGFR-TKI (gefitinib) treatment alone." (PMID 39735556, 2024). "Moreover, in some EGFR-mutated tumors, ICB may even lead to tumor hyperprogression." (PMID 39091494, 2024). "Consistently, IHC assays showed that TBC1D31 protein levels are significantly positively correlated with the levels of EGFR, p‐EGFR, p‐ERK1/2 and p‐AKT in subcutaneous tumor tissues from nude mice, and the HCC tissues from the VALI cohort (n = 168)." (PMID 39206796, 2024). "These cell lines were validated by EGFR expression at the mRNA and protein levels, phosphorylation of EGFR and its downstream signaling pathways, drug sensitivity to EGFR-TKI, cell proliferation in vitro and tumor growth in vivo." (PMID 39004699, 2024). "A paracrine EGFR/CSF-1R interaction exists between TAMs and tumor cells in which CSF-1 stimulates macrophages to release EGF, leading to tumor cell proliferation and migration." (PMID 39003350, 2024). "Muscarinic receptor M3 mediates transactivation of EGFR, activating signaling molecules like ERK1/2 and AKT, which promote tumor cell proliferation and invasion." (PMID 38567163, 2024). "The next step of this study was to evaluate the therapeutic effects of the EGFR TKI, osimertinib, in the three NSCLC tumor models Luc+ A549, Luc+ PC9 and Luc+ H1975." (PMID 38935790, 2024). "The first pathway is the signaling of epidermal growth factor receptor (EGFR), promoting cell proliferation, while its inhibition leads to tumor cell apoptosis." (PMID 39502961, 2024). "The EGFR and RAS/RAF signaling pathway plays pivotal roles in tumor progression via proliferation, survival, invasion, and immune evasion." (PMID 38982548, 2024). "In these patients, CXCR1 modulated the tumor microenvironment as well as the PI3K/AKT and ERK pathways, which are shared by CXCR1 and EGFR-TKI." (PMID 39114657, 2024). "PDT and PIT induce significant cell death and survival signalling (e.g. EGFR activation, VEGF secretion, priming cancer cells for concurrent molecular-targeted therapy (e.g. cetuximab), resulting in synergistic tumour reductions." (PMID 39261715, 2024). "The key to the mechanism of action is that after antibody binding, the cytotoxic payload can be directly delivered to tumor cells, limiting potential resistance mechanisms related to intracellular signaling, such as ME3 amplification in EGFR TKI resistance." (PMID 38429828, 2024). "It was indicated that β-Element, a traditional Chinese herb, played an anti-tumor and anti-metastatic role in multidrug-resistant (MDR) gastric cancer by suppressing EGFR levels through Cbl-b upregulation." (PMID 39048965, 2024). "Aberrant EGFR signaling, affecting the MAPK cascade, contributes to tumor invasion, metastasis, and progression." (PMID 38374954, 2024).